BOLA1 (bolA family member 1)
Description:
Acts as a mitochondrial iron-sulfur (Fe-S) cluster assembly factor that facilitates (Fe-S) cluster insertion into a subset of mitochondrial proteins (By similarity). Probably acts together with the monothiol glutaredoxin GLRX5. May protect cells against oxidative stress.
Synonyms: CGI-143
Tractability: PROTAC: ubiquitination databases record sites on it; its protein half-life has been measured.
Gene: Protein-coding gene on chromosome 1 (149,887,890 to 149,900,798, forward strand). Ensembl gene ENSG00000178096.
Subcellular location: Mitochondrion
Gene Ontology:
Molecular function: protein binding
Biological process: cell redox homeostasis; intracellular iron ion homeostasis; iron-sulfur cluster assembly
Cellular component: iron-sulfur cluster assembly complex; mitochondrion; cytoplasm
Genetic constraint (gnomAD): Loss-of-function variants: 6 observed, 6.87 expected, observed/expected ratio (o/e) 0.87, 90% interval 0.47 to 1.65. That is too few expected variants to judge how well the gene tolerates losing a copy. Missense variants: 183 observed, 194.44 expected, observed/expected ratio (o/e) 0.94, 90% interval 0.83 to 1.06. Synonymous variants: 87 observed, 90 expected, observed/expected ratio (o/e) 0.97, 90% interval 0.81 to 1.15.
Homologues: Orthologues: chimpanzee BOLA1 (99% identical), macaque BOLA1 (95% identical), rabbit BOLA1 (87% identical), pig BOLA1 (86% identical), rat Bola1 (82% identical), mouse Bola1 (81% identical), guinea pig BOLA1 (80% identical), dog BOLA1 (74% identical), zebrafish bola1 (50% identical), tropical clawed frog bola1 (47% identical), Drosophila melanogaster CG31126 (39% identical), Caenorhabditis elegans K11H12.1 (36% identical). Paralogues in human: BOLA2 (27% identical), BOLA2B (27% identical), BOLA3 (15% identical).
Diseases named in the same sentence as BOLA1 in open-access papers:
BOLA1 is named in the same sentence as 7 diseases in open-access papers, as found by Europe PMC text mining. Sharing a sentence is not in itself a finding about the gene and the disease. The quoted sentences say what the papers report.
ovarian carcinoma (2 papers, 2021 to 2023). A malignant neoplasm originating from the surface ovarian epithelium. "The elevated expression of BolA1, BolA2, and BolA3 was significantly associated with the prognosis of ovarian cancer patients." (PMID 36923798, 2023). "For BOLA1, the mRNA expression level was significantly higher in various kinds of ovarian cancer tissues than normal ovarian tissues in Lu′s dataset." (PMID 34078439, 2021).
cyst (1 paper, 2023). A sac-like closed membranous structure that may be empty or contain fluid or amorphous material. "Interestingly, the function of Grx5 and BolA1 may be stage-specific in G. intestinalis as their genes together with IscU are significantly upregulated at the cyst stage." (PMID 37792908, 2023).
Salmonella Infections (1 paper, 2025). Infections with bacteria of the genus SALMONELLA. "In the current work, we identified BOLA1 as one of the major downregulated mitochondrial proteins and DRP1 as one of the major upregulated mitochondrial proteins in the proteomic profiles of ELMO1-downregulated macrophages and in ELMO1 KO mice following Salmonella infection." (PMID 41250600, 2025).
cancer (1 paper, 2022). A tumor composed of atypical neoplastic, often pleomorphic cells that invade other tissues. "The number of the upregulation BOLA1\2\3 expression was found in tumors compared with normal tissues in various types of cancers." (PMID 36017386, 2022). "It has been suggested that BolA family members serve as assembly factors for mitochondrial iron-sulfur (Fe/S) cluster proteins that has involvement in cancer cell biology; although, the functions of BOLA1 and BOLA3 are still undefined in cancer." (PMID 36017386, 2022).
infection (1 paper, 2025). The state of being infected such as from the introduction of a foreign agent such as serum, vaccine, antigenic substance or organism. ",48In vitro experimental data revealed that the expression levels of BOLA1 decreased after SL infection and were significantly lower in E1 SLcompared to all uninfected cells." (PMID 41250600, 2025).
tumor (1 paper, 2022). "IntAct analysis revealed that BolA1/2/3 was closely associated with the GLRX3 expression in HCC, which is implicated in the regulation of the cellular iron homeostasis and tumor growth." (PMID 36017386, 2022).
BOLA1 also shares sentences with these, for which no sentence is quoted: theileriosis (1 paper).